LINC01939 (long independently transcribed non-coding RNA 1939)
Gene: Long non-coding RNA gene on chromosome 2 (899,462 to 905,539, reverse strand). Ensembl gene ENSG00000228799.
Diseases named in the same sentence as LINC01939 in open-access papers:
LINC01939 is named in the same sentence as 5 diseases in open-access papers, as found by Europe PMC text mining. Sharing a sentence is not in itself a finding about the gene and the disease. The quoted sentences say what the papers report.
gastric cancer (1 paper, 2022). A primary or metastatic malignant neoplasm involving the stomach. "For instance, LINC01939 directly binds to miR-17-5p and functions as a sponge of miR-17-5p to up-regulate the expression of EGR2 (the target of miR-17-5p) protein in gastric cancer." (PMID 35833119, 2022).
lymph node metastasis (1 paper, 2019). "Further analysis indicated that advanced TNM stage, lymph node metastasis and distance metastasis were negatively correlated with the expression of LINC01939, suggesting that LINC01939 may inhibit GC progression, particularly metastasis." (PMID 30683847, 2019).
cancer (1 paper, 2019). A tumor composed of atypical neoplastic, often pleomorphic cells that invade other tissues. "Primed by these results, we suggest that LINC01939 has a cancer-specific expression pattern and can act as a potential biomarker to help identify patients at a higher risk of GC metastasis." (PMID 30683847, 2019).
tumor (1 paper, 2019). "Low expression of LINC01939 was correlated with tumor metastasis and shorter survival in GC patients." (PMID 30683847, 2019). "In the present study, we found that reduced expression of LINC01939 is a common event in GC, indicating tumor suppressive role of LINC01939." (PMID 30683847, 2019).
LINC01939 also shares sentences with these, for which no sentence is quoted: cholangiocarcinoma (1 paper).